RELB (RELB proto-oncogene, NF-kB subunit)
Diseases named in the same sentence as RELB in open-access papers (continued):
Sharing a sentence is not in itself a finding about the gene and the disease.
lymphopenia (1 paper, 2021). Reduction in the number of lymphocytes. "FACS analyses 6 weeks after cell transfer revealed equivalent lymphoid tissue reconstitution and similar colon infiltration by Tconv, suggesting that RelB was dispensable for lymphopenia-induced proliferation and survival in immunocompromised hosts." (PMID 34608221, 2021). "In addition, RelB was dispensable for lymphopenia-induced proliferation and colon inflammation following transfer of Tconv to immunodeficient recipients." (PMID 34608221, 2021).
meningioma (1 paper, 2020). A generally slow growing tumor attached to the dura mater. "All of these findings led us to investigate the association of hypoxia, in addition to RELB, pSTAT3 and NFKB2 expressions with PD-L1 expression in our meningioma cohort." (PMID 32839486, 2020). "We observed high expression of NFKB2, RELB, pSTAT3, and positive CA9 expression in 30% (26/88), 26% (24/91), 63% (46/73), and 51% (37/72) of the meningioma cases, respectively." (PMID 32839486, 2020). "We then evaluated the expression of specific candidate proteins: NFKB2, pSTAT3, RELB, and CA9 by immunohistochemistry based on availability of the unstained slides and we correlated their expression with that of PD-L1 in our meningioma cohort." (PMID 32839486, 2020).
mesothelioma (1 paper, 2025). A usually malignant and aggressive neoplasm of the mesothelium which is often associated with exposure to asbestos. "Next, we employed an ELISA EMSA test to assess the DNA-binding activity of each NF-κB subunits, in the different cell lines, revealing a notable activity of DNA binding of p65 and RelB, which was intensified upon TNF-α treatment in mesothelioma cell lines IST-Mes2 and MPP89." (PMID 40016284, 2025).
metastasis (1 paper, 2018). The spread or migration of cancer cells from one part of the body (where they first appeared) to another. "High RelB expression was found in NSCLC patients in advanced stages of the disease with tumour invasion, lymph node metastasis, and distant metastases." (PMID 29983639, 2018).
Mycobacterium infection (1 paper, 2016). Infections with bacteria of the genus Mycobacterium. "The RelBE toxin/antitoxin system has been previously characterized in Mycobacterium infections, where RelB functions as an antitoxin that neutralizes the toxin RelE." (PMID 27662479, 2016).
ocular hypertensive (1 paper, 2024). "An exciting outcome of the NanoString-based gene profiling in ocular hypertensive samples included NF-κB components, as RelA (p65) decreased (p = 0.002) and RelB (p = 0.02) showed increased RNA counts in GFAP/cFLIP mice compared to controls." (PMID 38824526, 2024). "On the contrary, RelB expression and phospho-RelB were increased, supporting an upregulated transcriptional function of RelB in ocular hypertensive GFAP/cFLIP compared to ocular hypertensive controls." (PMID 38824526, 2024).
oral cancer (1 paper, 2020). "The other cytokine, LT-β, was also identified in this study; LT-β has been shown to correlate with human oral cancer, and additionally, it activates the NIK-IKKa-RELB/NF-κB2 pathway to stimulate HNSCC cell migration." (PMID 32961854, 2020).
Osteopenia (1 paper, 2022). Osteopenia is a term to define bone density that is not normal but also not as low as osteoporosis. "Consistent with this, deletion of RelB prevents the osteopenia phenotype in p100−/− mice associated with increased OB surfaces." (PMID 35235833, 2022).
pancreatic ductal adenocarcinoma (1 paper, 2016). An infiltrating adenocarcinoma that arises from the epithelial cells of the pancreas. "As a member of the NUPR1/RELB/IER3 survival pathway, may provide pancreatic ductal adenocarcinoma with remarkable resistance to cell stress, such as starvation or gemcitabine treatment." (PMID 27767172, 2016).
primary biliary cirrhosis (1 paper, 2022). "This protein is involved in the ductular reaction; the bile ducts of patients with primary sclerosing cholangitis and primary biliary cirrhosis exhibit increased levels of RelB." (PMID 36313114, 2022).
prostatic tumor (1 paper, 2015). "While p65 nuclear localization was increased in prostate tumors compared to normal adjacent tissues (p < 0.000, Wilcoxon test), RelB exhibited a higher expression in normal adjacent tissue vs. tumor tissue (p = 0.001, Wilcoxon test)." (PMID 26186215, 2015). "TMAs, containing patient-matched cores from 200 prostatic tumor tissues and normal adjacent epithelium were stained, scanned and evaluated for p65 and RelB positive signal." (PMID 26186215, 2015).
renal cell carcinoma (1 paper, 2018). "However, NIK and RelB have previously been shown to be crucial for B-cell development, suggesting that the non-canonical NF-κB pathway also plays a role and that RelB can modulate local inflammatory infiltrate in renal cell carcinoma." (PMID 30347849, 2018).
Respiratory tract infection (1 paper, 2021). An infection of the upper or lower respiratory tract. "Therefore, repeated respiratory tract infection is the main clinical feature of RelB deficiency." (PMID 33791233, 2021).
Salmonella Infections (1 paper, 2018). Infections with bacteria of the genus SALMONELLA. "During Salmonella infection, cleavage of the NF-κB subunits p65, RelB, and cRel by GtgA, GogA, and PipA inactivates these NF-κB subunits thereby inhibiting NF-κB–dependent gene transcription." (PMID 30049795, 2018).
small cell lung carcinoma (1 paper, 2018). Small cell lung cancer (SCLC) is a highly aggressive malignant neoplasm, accounting for 10-15% of lung cancer cases, characterized byrapid growth, and early metastasis. "Blocking RelB expression prevents the induction of Integrin β-1 expression and interferes with the attachment ability of small cell lung cancer H69 cells." (PMID 29983639, 2018).
spondyloarthropathy (1 paper, 2005). A group of inflammatory rheumatic diseases associated with arthritis and enthesitis, and often involving the axial skeleton. "We have previously shown that synovial tissue in RA and spondyloarthropathy is enriched in differentiated myeloid DCs that express CD33, CD11c, MHC class II, costimulatory molecules, and nuclear RelB." (PMID 15743469, 2005). "We conclude that the CD123+ cell population is most likely a pDC population that infiltrates RA and spondyloarthropathy but not normal synovial tissue and that it is distinct from the described nuclear RelB+ DCs." (PMID 15743469, 2005).
stomach adenocarcinoma (1 paper, 2020). "Consistent with the results in H. pylori-infected cells and INS-GAS mice, we found that the gene levels of IL-32, RELB and SLC7A11 were significantly increased in stomach adenocarcinoma tissues compared with those in normal tissues." (PMID 32457731, 2020).
Stroke (1 paper, 2012). Sudden impairment of blood flow to a part of the brain due to occlusion or rupture of an artery to the brain. "In addition, NFκB is a key molecule involved in stroke, and p50 and RelB proteins in CVECs were greater in SHRSP than in WKY or SHR." (PMID 23326018, 2012).
T-cell leukemia (1 paper, 2008). A malignant disease of the T-lymphocytes in the bone marrow, thymus, and/or blood. "In the present report we assessed the role of NF-κB proteins in a transgenic mouse model for human T-ALL induced by the TEL-JAK2 fusion protein and uncovered a specific role for RelB in T-cell leukemia development." (PMID 18596915, 2008). "Our data cannot discriminate whether RelB-dependent stromal cells facilitate the initiation or the progression of T-cell leukemia, or both." (PMID 18596915, 2008).
tongue cancer (1 paper, 2018). A malignant neoplasm affecting the tongue. "TSCC cell lines also showed similar strong expression of p50, p52, p65, c-Rel including RelB in both HPV+/−ve tongue cancer cells, however, the extent of c-Rel expression was distinctly higher in HPV−ve cells." (PMID 30250646, 2018).
Ureteral obstruction (1 paper, 2010). Obstruction of the flow of urine through the ureter. "Both p52 and RelB were part of NFκB DNA-binding complexes found in the kidney in mice with unilateral ureteral obstruction." (PMID 20126461, 2010).
uveal melanoma (1 paper, 2012). A melanoma derived from melanocytes of the uveal tract. "Although NF-κB transcription factor family genes including p65, NF-κB1, RelB, NF-κB2 and NIK were found to be expressed in both primary and metastatic uveal melanoma, the intact function, detailed activation and underlying mechanisms in uveal melanoma have not been well illustrated." (PMID 23443086, 2012).
tumor (109 papers, 2005 to 2026). "In one word, RelB was abnormally expressed in different cancer types and was closely associated with tumor immunity." (PMID 37388242, 2023). "The correlation between PD-L1 and RelB was associated with the pathological grades of tumour tissue samples." (PMID 35177112, 2022). "Accordingly, in vivo functional validation confirmed that RelB deficiency impairs tumor growth in nude mice and inhibits lung metastasis in SCID mice." (PMID 32807176, 2020). "In subcutaneous and intrabursal xenografts of OC cell lines with inducible knockdown of RelA or RelB with shRNA, loss of either RelA or RelB significantly reduced tumor burden compared to controls." (PMID 31443240, 2019). "In lung cancer, NIK is elevated and RelB associated with shorter overall survival, differentiation, tumour invasion, lymph node metastasis, distant metastasis and ‘tumour, node, metastasis’ (TNM) stage." (PMID 30347849, 2018). "Recently, RelB-p52 dimers were shown to regulate a group of nucleic acid editing enzymes (APOBECs) that are implicated in tumor progression." (PMID 29874793, 2018). "Increasing age, smoking exposure, and RelB and P50 expression were statistically significantly and positively associated with tumor extent, stage, and grade." (PMID 29371965, 2017). "To examine the association between upregulated RelB and tumor stage and histological type, we further analyzed the TMA-2 data and correlated RelB expression with clinicopathological parameters." (PMID 27711077, 2016). "RelB mRNA and p52 protein expression were also associated with the BCa tumor grade, clinical stage and lymph node metastasis profile." (PMID 25369740, 2015). "Our in vivo experiments with RelB transduced 22Rv1 PCa cells demonstrated that RelB expression caused a lag in tumor initiation, but only weakly affected the tumor growth rate once tumors had reach a volume of 500-mm3." (PMID 25788857, 2014). "We found that RelB expression caused a lag in 22Rv1 cells tumor initiation, although overall tumor growth in SCID mice was not affected." (PMID 25788857, 2014). "Here, we reveal that 40% of newly diagnosed MM patients have a constitutive RelB DNA-binding activity in CD138+ tumor cells, and we show an association with increased expression of a subset of anti-apoptotic NF-κB target genes, such as cIAP2." (PMID 23555623, 2013). "Then we took advantage of the TCGA database to analyze the relationship between RelB expression and DNA methylation, the infiltration of immune cells, immune checkpoint genes, tumor mutation burden (TMB), microsatellite instability (MSI), mismatch repair (MSS)." (PMID 37388242, 2023). "For example, c-REL may be a suitable target for GC tumours with strong NF-κB pathway activity, RELA for plasmablast-associated tumours, and RELB and/or NF-κB2 for the subset of DLBCL cases with nuclear translocation of these subunits." (PMID 36289712, 2022). "In addition, fibroblast-like cells, adjacent to tumour areas that were highly positive for V-ATPase expression, also showed an activated NF-Kb inflammatory pathway, as demonstrated by the presence of a RelB-associated nuclear signal." (PMID 34831016, 2021). "In contrast, three of the five BRCA1 ESR1-negative tumours, which showed the highest levels of NFκB2 and RELB expression, harboured missense mutations that might led to an aberrant but still present BRCA1 protein." (PMID 19826428, 2009). "In contrast, 60% of the ESR1-negative tumours (group B), which show the highest expression of NFκB2 and RELB, harboured missense mutations in BRCA1, which could produce aberrant proteins but conserving some activities such as the capacity to activate the NFκB machinery." (PMID 19826428, 2009). "Using a neutrophil-tumor cell co-culture system, we found that RELB knockdown in neutrophils attenuated inflammatory signaling in tumor cells and subsequently reduced their proliferative, clonogenic, migratory, and invasive capacities." (PMID 41783590, 2026).
tumor (continued). "The functional role of the key regulator RELB was validated using siRNA-mediated knockdown in neutrophil-tumor cell co-culture systems, assessed by qPCR, proliferation, clonogenic, migration, and invasion assays." (PMID 41783590, 2026). "Single-cell transcriptomic analysis and multiplex staining in primary tumors reveal distinct spatial and cellular distribution patterns, with RELA and RELB active in separate tumor and microenvironmental compartments." (PMID 41844578, 2026). "The NFκB transcription factor is a crucial regulator of tumor metastasis and growth, typically functioning as a heterodimer or homodimer of RelA/p65, RelB, p52, p50, and c-Rel." (PMID 40260225, 2025). "Within the tumour epithelial cells, however, various NFκB related signalling pathways had corresponding upregulation such as IκKα, RelB and HIF1α." (PMID 39068768, 2024). "Consistently, X‐ray imaging confirmed reductions in bone density by bone loss as the tumour increased, but reducing S100A4 unequivocally protected against net bone loss by alleviating the metastatic capacity of RelB." (PMID 39415352, 2024). "We observed elevated expression NIK along with p52 and RelB (primarily in the nucleus) in mouse tumor tissues expressing the PUM1-TRAF3 fusion protein, regardless of TRAF3 expression." (PMID 39090283, 2024). "Reduced expressions of c-myc, PD-L1, and RelB proteins were observed in THF-treated MC38 tumor tissues compared with the control group." (PMID 37924094, 2023). "Meanwhile, RelB correlated with the tumor genesis related pathway, suggesting RelB promote the process of tumor genesis in human pan-cancer." (PMID 37388242, 2023). "Here, the results showed RelB was positively correlated with the abundance of the infiltrating macrophages and monocytes, which displayed the complexity of the tumor immune environment." (PMID 37388242, 2023). "We then focused on the relationship between RelB expression and tumor-infiltrating immune cell or tumor immune microenvironment." (PMID 37388242, 2023). "The antitumor function of 3',4',7,8-tetrahydroxyflavone (THF), a specific BRD4 inhibitor, was studied through in vivo tumor model and mouse studies, and the protein levels of c-Myc, PD-L1, and RelB were examined in tumor model under THF treatment." (PMID 37924094, 2023). "In OV90 spheres with miR-452-5p inhibited, sphere formation was significantly decreased in the shNeg control, RELA-silenced, and RELB-silenced cells compared to controls, which is consistent with its role as a tumor-promoting miRNA." (PMID 37175530, 2023). "THF reduced the MC38-derived and 4T1-derived tumor volume and weight, and the inhibitor-treated tumor showed reduced expression levels of c-Myc, PD-L1, and RelB." (PMID 37924094, 2023). "The vertebrate Rel/NF-kB transcription factors (c-rel, RelA, RelB, NF-kB1 (p50/p105) and NF-kB2 (p52/p100)) play vital roles in immune, inflammatory/stress responses, and are key to tumor survival." (PMID 35742868, 2022). "These tumours displayed RELB DNA-binding activity, as determined by EMSA, and a distinct gene expression profile enriched in genes linked to cell death and survival, metabolism, immune cell trafficking, inflammation, and proliferation." (PMID 36289712, 2022). "Regardless of endogenous mouse PD-L1, the levels of PD-L1 in RelB-KO tumours were significantly reduced, but the levels were raised in RelB-KO/PD-L1 tumours." (PMID 35177112, 2022). "Correspondingly, knockdown of NIK significantly inhibited IR‐induced activation of the non‐canonical NF‐KB signaling pathway in PELI1‐knockdown tumor cells, manifested by the inhibition of RelB and p52 nuclear translocation upon IR treatment." (PMID 34738714, 2022). "LTB also plays a role in mediating RELB and nuclear factor-κB-2, components of the alternative nuclear factor-κB pathway; this alternative pathway promotes tumor cell migration that is an important feature of metastasis." (PMID 36567723, 2022).